IL6 (interleukin 6)
Diseases named in the same sentence as IL6 in open-access papers (continued):
Sharing a sentence is not in itself a finding about the gene and the disease.
Insulin resistance (continued). "Notably, in this model, hyperhomocysteinemia leads to elevations in TNF-α, IL-6, and MCP-1 and exaggerates insulin resistance, risk factors for cardiovascular diseases observed in PCOS." (PMID 37195871, 2023). "Studies have shown that HP infection induces the release of pro-inflammatory cytokines such as tumor necrosis factor alpha, interferon gamma, interleukin (IL)-1, IL-6, IL-8, IL-10, IL-12, and C reactive protein and was shown to be involved in the pathogenesis of insulin resistance." (PMID 36699110, 2023). "Moreover, IL-6, a proinflammatory cytokine, has been shown to induce gluconeogenesis subsequent to hyperglycemia and peripheral insulin resistance." (PMID 38004306, 2023). "Based on our findings, there appears to be a noteworthy and affirmative correlation between serum levels of CCN5 and the risk of developing GDM, as well as its associated risk factors such as BMI, insulin resistance index, FBG, and inflammatory cytokines TNF-α and IL-6." (PMID 37794318, 2023). "This suggests that CCN5 may play a role in the development of GDM, as there was a direct and significant correlation between CCN5 and several risk factors for GDM, including BMI, insulin resistance index, FBG, and inflammatory cytokines (IL-6 and TNF-α)." (PMID 37794318, 2023). "In addition, inflammatory cytokines (tumor necrosis factor-alpha and interleukin-6) released by macrophages accumulated in visceral adipose tissue can weaken insulin sensitivity and thus promote insulin resistance." (PMID 37674809, 2023). "Adipocytes and resident macrophages that have migrated to the adipose tissue produce and secrete adipocytokines, including tumor necrosis factor-α, interleukin-6, resistin, and adiponectin, which are thought to contribute to the development of insulin resistance and T2D." (PMID 37680885, 2023). "Importantly, although insulin-resistant adipocytes have been shown to increase expression of TNF-α, IL-6, and IL-8, only IL-6 released into the systemic circulation induces insulin resistance in the liver and the production of C-reactive protein." (PMID 37664841, 2023). "However, IL-6 manifests a dual action against insulin resistance, while the cytokine enhances glucose uptake, serum IL-6 can predict the development of T2DM." (PMID 37996879, 2023). "TNF-α, IL-1β, and IL-6 released by adipose tissue resident macrophages could lead to insulin resistance." (PMID 37693353, 2023). "Our research indicates a noteworthy and affirmative correlation between the levels of CCN5 in the serum and the risk of developing GDM, along with its associated risk factors such as BMI, insulin resistance index, FBG, and inflammatory cytokines (TNF-α and IL-6)." (PMID 37794318, 2023). "The reduced level of miR-124 could promote progression to T2DM through interactions with NF-κB, TRAF-6, and cytokines (TNFα and IL-6), which lead to insulin resistance, poor glycemic control, and a pro-inflammatory state." (PMID 37628595, 2023). "Inflammatory cytokines such as TNF-γ and IL-6 as well as the chemokine CCL2, produced by proinflammatory M1-like AT macrophages and hypertrophic adipocytes inhibit local insulin signalling pathways to cause adipose and systemic insulin resistance." (PMID 37642146, 2023). "It has been reported that RAS activation in the liver promotes insulin resistance, lipogenesis, and the production of proinflammatory cytokines such as interleukin-6 (IL-6) and tumor growth factor-β (TGF-β), which induces fibrogenesis and causes histological changes typical of NASH." (PMID 37062837, 2023). "The putative mechanisms of sarcopenia in patients with HCC are complex and are related to chronic inflammation, including tumor necrosis factor-α and interleukin-6, insulin resistance, and low levels of vitamin D, which lead to the progression of liver fibrosis and HCC." (PMID 37895312, 2023).
Insulin resistance (continued). "Additionally, IL-1 has been demonstrated to be implicated in pancreatic cell destruction, whereas tumor necrosis factor seems to be a critical molecule in peripheral insulin resistance and IL-6 has a direct influence on glucose and lipid metabolism." (PMID 36674154, 2023). "Because adipose tissue with an excessive amount of FFA, resistin, TNF-α, interleukin-6, and other substances might result in insulin resistance." (PMID 37763170, 2023). "Research now shows that TNF-α and IL-6 are fat factors which induce insulin resistance." (PMID 36997952, 2023). "TNF-α and IL-6 are considered the main inflammatory mediators of insulin resistance, which can activate various inflammatory signaling pathways, inhibit insulin signaling, and lead to insulin resistance." (PMID 36986084, 2023). "We focused on the protein levels of proinflammatory cytokines such as NF-κB, TNF-α, INF-γ, and IL-6 in both control and experimental rats to ascertain whether kiwi extract can lessen inflammation and insulin resistance brought on by HFD and STZ." (PMID 37762060, 2023). "In addition, MAP4K4 in T cells can phosphorylate TRAF2, thus downregulating the expression of IL-6, leading to the inhibition of Th17 differentiation and preventing insulin resistance." (PMID 36875140, 2023). "Then, it could be explained through resistin’s effect in inflammation-induced insulin resistance, probably due to its activity over inflammatory cytokines, such as IL6, IL-12, TNF-α, and (NF-κB)." (PMID 37238961, 2023). "IL-15 and IL-6 are cytokines secreted by skeletal muscle cells, addition to the immune cells during immune responses, and are involved in the pathogenesis of autoimmune diseases and insulin resistance." (PMID 37876013, 2023). "The observed results in this study regarding the serum TNF-α and IL-6 levels could be explained by the metabolic disturbances induced by DEXA that led to an insulin resistance state; this was observed in similar animal studies." (PMID 37894792, 2023). "Moreover, SOCS3 ubiquitinates IRS-1 to induce its degradation, leading IL-6 to induce insulin resistance." (PMID 37555019, 2023). "Such systemic inflammation was described as developing due to the accumulation of adipose tissue in the abdominal area, which activates macrophages, endothelial dysfunction, excessive production of tumor necrosis factor α, interleukin-6 and adipocytokines, oxidative stress, and insulin resistance." (PMID 37238705, 2023). "Along with increased body weight and insulin-resistance conditions, serum proinflammatory cytokines, including IL-6 and TNF-α, also showed a significant increase in comparison with the ND group, which were reversed after treating mice with orlistat and both doses of O. aristatus for two months." (PMID 36678606, 2023). "In addition to releasing free fatty acids, which affect blood glucose, fat also releases substances such as leptin, lipocalin, resistin, tumour necrosis factor-α and interleukin 6, which contribute to the development of insulin resistance." (PMID 37089923, 2023). "Insulin resistance and adipose tissue hyperplasia, on the other hand, are considered inflammatory states that are associated with elevated proinflammatory mediators and cytokines, e.g., TNF-α and IL-6." (PMID 37764820, 2023). "Hesperidin could also affect insulin levels and insulin resistance by modulating inflammation since it has been shown that inflammatory markers, including leptin, IL-6, and TNF-α, play a role in the pathogenesis of DM and the development of insulin resistance." (PMID 37502716, 2023). "In the case of IL6, insulin resistance and stimulation of IL6 seem to be mechanistically related." (PMID 37063831, 2023). "Moreover, the elevation in circulating IL-6, TNF-a, and CRP levels caused by periodontitis contributes to increased systemic inflammation, thus further aggravating insulin resistance in patients with T2DM." (PMID 38098816, 2023).
Insulin resistance (continued). "IL-6 may be also involved in the pathogenesis of hepatic insulin resistance as insulin sensitivity increases in diet-induced obese mice treated with anti-IL-6 antibodies." (PMID 37999226, 2023). "IL-6 exacerbates insulin resistance by activating STAT-3 in hepatocytes." (PMID 37996879, 2023). "Treatment with C. odorata and coumarin offered an anti-hypertensive effect and caused modulation in insulin resistance, possibly through its effect on amended oxidative stress biomarkers (SOD, CAT, and MDA), inflammatory mediators (TNF-α and IL-6) and improved insulin sensitivity." (PMID 37033655, 2023). "As an endocrine organ, visceral adipose tissue (VAT) has been reported to be biologically active; excessive VAT contributes to considerable insulin resistance, expresses larger numbers of androgen receptors, and releases higher levels of adiponectin and IL-6 than subcutaneous adipose tissue." (PMID 36713086, 2023). "Indeed, several studies have reported increased levels of TNF-α, IL1-β, and IL-6 in adipose tissue that can lead to insulin resistance." (PMID 37892881, 2023). "This improvement in insulin resistance may be linked to SSFR-associated changes in the secretion of certain adipokines, such as leptin and IL-6." (PMID 37021835, 2023). "Treatment with 50 mg/kg CBD oil by oral gavage was able to reduce white adipose tissue and revert insulin resistance in males, reduce plasma triglycerides in females, and attenuate plasma LPS levels and overexpression of TNFα and IL6 in the hypothalamus of both sexes." (PMID 36969815, 2023). "IL-6 has is a pro-inflammatory cytokine that induces the development of insulin resistance." (PMID 37139450, 2023). "The higher prevalence of T2DM in COPD patients, even in mild cases and independent of steroid use, may be attributed to elevated levels of inflammatory mediators such as TNF-a and IL-6, which can lead to insulin resistance." (PMID 37900064, 2023). "MAP4K4 downregulates IL-6 production in T cells through direct phosphorylation and degradation of TNF receptor-associated factor 2 (TRAF2), leading to the suppression of Th17 cell-mediated insulin resistance in vivo." (PMID 36568222, 2022). "As PRL concentrations increase within the physiologic range, IL-6 release into the tissue decrease, leading to an inflammatory state that might aggravate insulin resistance." (PMID 36471299, 2022). "Since this study used secondary data derived from the KNHANES, we could not collect data on sex hormone prescriptions, such as estrogen or testosterone; inflammatory markers, such as CRP or IL-6; or insulin resistance markers, such as HOMA-IR." (PMID 36362539, 2022). "By inhibiting the expression of the insulin receptor, insulin receptor substrate-1, and glucose transporter type 4 in 3T3-L1 adipocytes, IL-6 suppresses insulin activity A correlation has been shown between increased IL-6 levels and the occurrence of insulin resistance." (PMID 36248900, 2022). "IL-6 has various functions and was shown to contribute to hepatic insulin resistance." (PMID 35052810, 2022). "IL-6 promotes T cell population expansion, B cell differentiation, and proliferation of many cells it can also regulate the acute phase response and various homeostasis functions, including glucose metabolism, lipid metabolism, and insulin resistance." (PMID 35866786, 2022). "Indeed, Pearson's correlations analysis revealed that the variation in gut microbial composition was highly correlated to insulin resistance, IL‐6, and LPS levels." (PMID 36348812, 2022). "With the induction of lipopolysaccharide and saturated fatty acid, M1 macrophages can activate and secrete tumor necrosis factor α (TNF-α), interleukin-6 (IL-6), interleukin-12 (IL-12), interleukin-1β (IL-1β) and other pro-inflammatory factors, leading to inflammation and insulin resistance." (PMID 35757707, 2022).
Insulin resistance (continued). "Interestingly, high blood levels of pro-inflammatory cytokines IL-6, IL-1B, and high sensitivity C-reactive protein (hsCRP), a clinical marker of inflammation, in obese patients are predictors of insulin resistance and hyperglycemia." (PMID 36247456, 2022). "In addition, adiponectin, which negatively correlates with BMI, counteracts insulin resistance and exerts anti-inflammatory effects by inhibiting the expression of IL-6 or tumor necrosis factor alpha (TNFα)." (PMID 35323701, 2022). "The increase of the diabetes risk factor as far as hepatitis C virus is concerned seems to be associated with insulin resistance and chronic inflammatory reaction resulting from the increased synthesis of pro-inflammatory cytokines—mainly Tumour Necrosis Factor (TNF) alfa and interleukin 6 (IL-6)." (PMID 35054072, 2022). "Also, they mentioned that insulin resistance resulted in a significant difference in the IL-6 (interleukin-6) levels." (PMID 35986233, 2022). "Other data suggest that IL-6 may be in-volved in inflammation and insulin resistance, while TNF-α may induce the progression of NAFLD and promote the development of steatohepatitis." (PMID 36432495, 2022). "When the butyrate produced by the GM decreases, the intestinal mucosa is damaged, permeability increases or immunity is imbalanced, immune cells infiltrate, and pro-inflammatory cytokines (INF-a, IL-6) increase, activating the inflammatory signaling pathway and leading to insulin resistance and GDM." (PMID 34302684, 2022). "Chronic toxoplasmosis was suggested to play a role in the pathogenesis of type 2 diabetes mellitus (T2D) due to the correlation between the state of insulin resistance in T2D and the elevated levels of circulating inflammatory cytokines including IL-2,4; IL-6,5; IL-12,6; TNF; and IFN." (PMID 36672526, 2022). "Thus, it can reduce fasting blood glucose and insulin resistance and reduce inflammation by decreasing serum levels of IL-6, TNF-α, and resistin and increasing serum levels of adiponectin and irisin, which ultimately improve insulin sensitivity." (PMID 36355818, 2022). "In addition, IL-6 is one of the adipokines that promotes insulin resistance and dyslipidemia in humans, and TNF-α is the driver behind dyslipidemia." (PMID 35872979, 2022). "Lp(a) levels have been demonstrated to be more correlated to IL-6 compared with metabolic parameters, such as body mass index, insulin resistance, and triglyceride, indicating that Lp(a) serum concentrations are not only genetically determined but are also influenced by IL-6." (PMID 35096275, 2022). "This reduction of adipogenesis by Sirt3 inhibitor was associated with increased proinflammatory cytokines including IL6, resistin, and TNF, suggesting Sirt3 downregulation might increase the risk of insulin resistance and metabolic abnormalities." (PMID 35409099, 2022). "Chronic exposure to IL-6 selectively induces insulin resistance in the liver." (PMID 35711703, 2022). "Finally, the cytokine interleukin-6 (IL-6) signals through the JAK/STAT pathway, and IL-6 overexpression in obese patients has been shown to mediate insulin resistance." (PMID 36230617, 2022). "In addition, IL-6 can also induce insulin resistance by reducing insulin sensitivity, or by affecting lipid metabolism." (PMID 35846289, 2022). "Thirdly, through oxidative stress hyperglycemia enhances the circulating concentrations of proinflammatory cytokines, such as tumor necrosis factor-α (TNF-α) and interleukin-6 (IL-6), leading to insulin resistance and resulting in malicious exacerbation of hyperglycemia." (PMID 35600601, 2022). "Increased IL-6 inhibits insulin signalling and leads to insulin resistance, mainly in the liver." (PMID 35711703, 2022). "However, there are various other inflammatory cytokines, such as IL-6, which are related to insulin resistance apart from TNF-α." (PMID 34997408, 2022).
Insulin resistance (continued). "When IL-6 is produced by the skeletal muscle it increases insulin sensitivity whereas its (IL-6) release from adipocytes and macrophages leads to an increase in insulin resistance." (PMID 36778598, 2022). "Among the three inflammatory cytokines, IL-6 might be the most likely mediator relating FM and insulin resistance at baseline." (PMID 36140983, 2022). "Besides, interleukin-6 (IL-6) can impair the phosphorylation of insulin receptors and insulin receptor substrate which leads to insulin resistance." (PMID 36258686, 2022). "Previously it was reported that IL-6, especially TNF-α, may have an important role in the etiology of diabetes and insulin resistance, and IL-6 levels may increase 2–3 times." (PMID 34174798, 2022). "Elevated IL-6 release might contribute to diabetes progression, as an in vitro study reported the induction of cellular insulin resistance of hepatocytes by IL-6-triggered impairment of insulin receptor signal transduction." (PMID 35163309, 2022). "In addition, previous studies found that resistin was weakly correlated with other inflammatory molecules such as TNF-α, IL-6, insulin, and insulin resistance measured by homeostasis model assessment-insulin resistance (HOMA-IR)." (PMID 36428592, 2022). "IL-6 is also positively correlated with hyperglycemia and insulin resistance/sensitivity indices." (PMID 36145254, 2022). "SAS correlates with diabetes, hypertriglyceridemia, increased interleukin-6 (IL-6), insulin resistance, fatty liver, liver fibrosis, and inflammation, high density lipoprotein-cholesterol (HDL-C), but not with cholesterol, triglycerides (TG), or low-density lipoprotein-C (LDL-C)." (PMID 36438601, 2022). "In addition, higher IL6 levels increase the risk of CVD, diabetes, and insulin resistance in obese patients." (PMID 35955698, 2022). "Proinflammatory cytokines (IL-1β, IL-6) have multiple effects on many events including the initiation and maintenance of inflammation, endothelial dysfunction, metabolic syndrome, insulin resistance, diabetes mellitus, oxidative stress and cardiovascular events." (PMID 36326375, 2022). "On the other side, high-intensity PA induced an improvement in inflammatory biomarkers and insulin resistance, with a reduction in IL-6, TNFa, CRP, and resistin and an increase in adiponectin, thus indicating that exercise exerts anti-inflammatory and insulin-sensitising effects." (PMID 35679338, 2022). "In these circumstances, the increased IL-6 levels might be detrimental and correlated with metabolic syndrome and insulin resistance in humans and mice." (PMID 36452038, 2022). "In addition, it has been found that muscle-derived IL-6 improves insulin resistance through activating AMPK and inhibiting the p38/MAPK signaling pathway." (PMID 36091401, 2022). "The proinflammatory M1 macrophages are capable to secrete TNF-α and IL-6 which may lead to insulin resistance and CXCL16 upregulation." (PMID 35784287, 2022). "Except for that, IL-6 is also closely related to metabolic syndrome and insulin resistance." (PMID 36091401, 2022). "Moreover, pro-inflammatory cytokines such as TNF-α and IL-6 interfere with the insulin signaling pathway and increase insulin resistance under stress conditions." (PMID 36079032, 2022). "On the other hand, pro-inflammatory cytokines such as interleukin-6 (IL-6) have been suggested to contribute to the overall development of insulin resistance and could have a role in the etiology of GDM." (PMID 36235652, 2022). "Several studies have shown that acupuncture can improve insulin resistance by reducing serum IL-6, IL-8, and IL-1β levels, which might help protect islet B cell function." (PMID 37675019, 2022). "IL-1β and IL-6 have been shown to induce insulin resistance in adipocytes." (PMID 35625866, 2022). "We demonstrated a significant relationship of IL-6 with FM and insulin resistance at baseline." (PMID 36140983, 2022).